OTUB1 (OTU deubiquitinase, ubiquitin aldehyde binding 1)
Diseases named in the same sentence as OTUB1 in open-access papers (continued):
Sharing a sentence is not in itself a finding about the gene and the disease.
papillary thyroid carcinoma (1 paper, 2021). "Therefore, we investigated the clinical relevance and underlying role of OTUB1 in papillary thyroid carcinoma." (PMID 34773364, 2021). "However, the function of OTUB1 in papillary thyroid cancer (PTC) and the underlying mechanisms regulating PTC cells proliferation remain poorly understood." (PMID 34773364, 2021). "In this study, OTUB1 was significantly upregulated in papillary thyroid carcinoma tissues and cells." (PMID 34773364, 2021). "However, the function of OTUB1 in papillary thyroid cancer remains elusive." (PMID 34773364, 2021).
prostate tumor (1 paper, 2022). "Expression profiling analysis suggested that the expression of UBE2M and OTUB1 was significantly increased in prostate tumor tissue samples compared with normal tissues." (PMID 35864871, 2022).
toxoplasmosis (1 paper, 2021). A parasitic disease contracted by the ingestion or fetal transmission of toxoplasma gondii. "To address the importance of OTUB1-mediated NF-κB activation in vivo, we studied a murine model of toxoplasmosis because protection against T. gondii is critically dependent on TgPFN-mediated activation of TLR11/12 in DCs." (PMID 32024978, 2021). "To determine the functional role of OTUB1 in DCs in vivo, we induced toxoplasmosis in CD11c-Cre OTUB1fl/fl and control mice." (PMID 32024978, 2021). "Together, these data suggest a pivotal role for OTUB1 in driving NF-κB-dependent immune reactions in DCs, including IL-12 production, which is critical for a potent NK cell-dependent IFN-γ response in toxoplasmosis." (PMID 32024978, 2021).
type 2 diabetes (1 paper, 2022). "Our results highlight the physiological relevance of this DUB, indicate that OTUB1 is a relevant target protein of FIH in vivo and suggest that OTUB1 may be a novel therapeutic target for the treatment of type 2 diabetes, which needs to be investigated further in the future." (PMID 35163456, 2022).
Yersinia infection (1 paper, 2021). "For instance, during Yersinia infection, otubain 1 (OTUB1) can disassemble the Lys48-linked polyubiquitin chains from GTP-RhoA to maintain its stability." (PMID 34277632, 2021). "While prior to Yersinia infection, wild-type OTUB1 catalyzes the deubiquitination of active-form RhoA to stabilize the protein, and then enhances the cellular susceptibility to invasion." (PMID 34277632, 2021).
cancer (86 papers, 2014 to 2025). A tumor composed of atypical neoplastic, often pleomorphic cells that invade other tissues. "Aberrant OTUB1 function is implicated in various diseases, including cancer, neurodegenerative disorders, and autoimmune conditions." (PMID 39500879, 2024). "While the association of OTUB1 in various cancers has been extensively studied, ongoing efforts to target this protein with inhibitors are in progress." (PMID 38663827, 2024). "It has been reported that SLC7A11 is closely associated with cancer ferroptosis induced by lipid peroxidation, and OTUB1 improves SLC7A11 stability by removing the ubiquitin modification." (PMID 37190313, 2023). "OTUB1 deubiquitinase function was recently associated with the regulation of immune responses and contributes to immunosuppression in cancers via the programmed death ligand 1 (PD-L1) protein." (PMID 37892185, 2023). "Dub OTUB1 can inhibit the K48-linked ubiquitination level of Programmed Death Ligand1 (PD-L1) and affect the immunosuppression of cancer by regulating the stability of PD-L1." (PMID 36778143, 2023). "In malignancies, OTUB1 was found to elevated its expression in several human cancers, which expression was also associated with poor survival in quite a few studies." (PMID 36271031, 2022). "This regulation of DNA damage signaling factors in genome stability underscores OTUB1’s importance in cancer susceptibility and therapy." (PMID 33640455, 2021). "Otub1 has been reported in many cancer tissues and negatively associated with poor prognosis of cancer patients." (PMID 33627137, 2021). "In agreement, the overexpression of OTUB1 has been shown to be associated with poorer outcome and cancer progression." (PMID 26148240, 2016). "Given that importance of hypoxia signaling in metabolism, cancer progression, and other multiple physiological processes, to investigate the role and the underlying mechanism of OTUB1 in these processes will open a new window for understanding the physiological relevance of OTUB1." (PMID 35732631, 2022). "Otub1 deficiency was associated with anti-cancer immunity and loss of self-tolerance." (PMID 35747794, 2022). "Moreover, OTUB1 was recently reported to promote cancer cell immunosuppression by preventing ER-associated degradation of the immune checkpoint protein PD-L1." (PMID 35864871, 2022). "Indeed, OTUB1 is frequently overexpressed in multiple types of cancer, and OTUB1 deficiency abolishes xenograft growth in mice, which can be rescued by SLC7A11 overexpression." (PMID 34485285, 2021). "MicroRNAs significantly affect the progression and invasion of various cancers by targeting OTUB1 mRNA." (PMID 39785769, 2025). "OTUB1, which is overexpressed in multiple human cancers, directly interacts with SLC7A11 to remove its ubiquitination marks, preventing proteasome-mediated degradation and increasing its stability, thus inhibiting the activation of ferroptosis." (PMID 39769177, 2024). "OTU deubiquitinase B1(OTUB1), an atypical deubiquitinase prevalent in numerous human cancers, principally stabilizes SLC7A11 by impeding its ubiquitination and subsequent proteasomal degradation." (PMID 38515565, 2024). "The presence of a binding site in the OTUB1 promoter for TFAP2A suggested an enhanced overexpression of OTUB1 when high levels of TFAP2A are detectable in cancer cells." (PMID 37132605, 2024). "Taken together, these findings support the important role of OTUB1 in regulating the response of cancer cells to cisplatin chemotherapy through β-catenin stabilization." (PMID 39113709, 2024). "Mounting evidence substantiates the pivotal role of OTUB1 in the regulation of lung development, DNA damage repair, respiratory control, and cancer metastasis." (PMID 38977909, 2024). "USP43, USP52, JOSD1, UCHL5 and OTUB1 all reduced levels of the HIF-1α target CA9 in the secondary validation screen in two different non-cancer cell lines." (PMID 39009674, 2024).
cancer (continued). "Previous comprehensive studies have shown the pivotal role of OTUB1 in cancer initiation, DNA damage response, energy metabolism, and pulmonary fibrosis." (PMID 38977909, 2024). "Multiple studies have shown that dysregulated OTUB1 is involved in the tumorigenesis, progression and chemoresistance of several cancers through stabilizing some proteins." (PMID 39113709, 2024). "The OTUB1-high expression group displayed significant elevation of several cancer-promoting pathways, including CELL_CYCLE, TIGHT_JUNCTION, and PI3K_AKT_MTOR_SIGNALING." (PMID 38315284, 2024). "As the activation of c-MYC contributes to the progression of multiple types of cancer, this study implies a general tumor-promoting role of OTUB1." (PMID 38264570, 2023). "OTUB1 expression is regulated by multiple factors in cancer, including non-coding RNA and transcription factors.OTUB1 in turn can either promote or suppress malignancy in cancer through deubiquitinating multiple effectors." (PMID 38264570, 2023). "In conclusion, Syk/SHP2/Src/OTUB1 axis-mediated signaling can act as a therapeutic target in cancer management." (PMID 37330581, 2023). "This led to the SHP2-dependent dephosphorylation of Src and OTUB1, and ODN-induced Syk activation increased sensitivity to the anti-cancer drug through regulation of SHP2/OTUB1/Raptor axis." (PMID 37330581, 2023). "Previous studies have shown OTUB1 contributes to cancer cell survival, proliferation, migration, and invasion." (PMID 38264570, 2023). "Together, the Syk/SHP2/Src/OTUB1 axis contributed to ODN-induced anti-cancer drug sensitization via Raptor degradation." (PMID 37330581, 2023). "This study emphasizes Raptor downregulation as an upstream regulator of the anti-cancer drug enhancement effect, which is regulated by Src-dependent dephosphorylation of OTUB1 at Y26." (PMID 37330581, 2023). "OTUB1 has emerged as a versatile deubiquitinase that plays critical roles in physiological and pathophysiological processes including development, cancer progression, immune response, and DNA damage response." (PMID 38264570, 2023). "Given the importance of hypoxia signaling in cancer initiation and progression, to get insights into the biological function of OTUB1 mediated by its effect on hypoxia signaling, we sought to look into its expression in cancer tissues." (PMID 35732631, 2022). "In cancers, OTUB1 was proved to promote cancer progression via stabilizing ATF6 protein and PDL1 for cancer cell immune evasion." (PMID 36271031, 2022). "The identification of OTUB1 as a stabilizer of c-MYC reveals a new potential target for treating c-MYC in cancers." (PMID 35159073, 2022). "OTUB1, the OTU domain-containing ubiquitin aldehyde-binding protein 1, was described to possess a pivotal role in cancer induction and progression." (PMID 36335372, 2022). "The Propidium Iodide (PI) coupled with Annexin V staining showed that OTUB1 depletion facilitated cancer cell apoptosis in AGS and MKN28 cells." (PMID 36271031, 2022). "The CCK8 assay showed that OTUB1 depletion inhibited cancer cell proliferation in AGS and MKN28 cells." (PMID 36271031, 2022). "Functionally, the OTUB1-SLC7A11 axis was critical for tumor growth and OTUB1 inactivation promotes ferroptosis in human cancer cells primarily by down-regulating SLC7A11 levels." (PMID 35307036, 2022). "Subsequent investigation in multiple CRC cancer and normal human mucosa cell lines indicated that OTUB1 was highly expressed in all tumor cell lines (SW620, HCT116, SW480, RKO, LOVO, DLD1), in comparison with mucosa cell line FHC." (PMID 35354355, 2022). "Stem cell marker CD44 expression suppresses ferroptosis in cancer cells in an OTUB1-dependent manner by promoting the interaction between SLC7A11 and OTUB1." (PMID 36551253, 2022).
cancer (continued). "Silencing OTUB1 can significantly inhibit cancer status and metastasis, and targeting OTUB1 would be an excellent target for numerous cancer patients." (PMID 35715413, 2022). "UBE2M and OTUB1 are both cancer-related genes and have been reported to regulate the immune response and antitumor immunity." (PMID 35864871, 2022). "Our analysis indicates that OTUB1 acts as an oncogene in this c-MYC-dependent cancer type and that overexpression of OTUB1 increases c-MYC protein levels." (PMID 35159073, 2022). "In renal cell carcinoma, for example, OTUB1‐derived deubiquitylation of FOXM1 can promote cancer cells growth and metastasis." (PMID 34773364, 2021). "Recently, more DUBs, such as ubiquitin-specific peptidase 9 X-linked (USP9X), USP22, and OTU domain ubiquitin aldehyde binding 1 (OTUB1), were found to deubiquitinate and stabilize PD-L1 in different cancers." (PMID 34829931, 2021). "OTUB1 has complex functions in various cancers, promotes tumor migration, and is a tumor suppressor that induces cell apoptosis and cell growth by regulating the DNA damage response." (PMID 34790661, 2021). "BoyiGan and colleagues demonstrated that overexpression of the deubiquitinase ovarian tumor (OTU) family deubiquitinase ubiquitin aldehyde binding 1 (OTUB1) in human cancers can promote tumor progression by regulating the ferroptosis process in cancer cells." (PMID 34115610, 2021). "Recently, OTUB1 has emerged as essential modulators of multiple carcinomas progression and accumulating evidences suggest that OTUB1 plays an essential role in negatively regulating ubiquitination to enhance stability of proteins." (PMID 34773364, 2021). "We found that the expression level of OTUB1 can significantly impact the expression of most of the immune marker sets of various immune cells in both tumor and cancer tissues." (PMID 33240928, 2020). "Due to the functional complexity of OTUB1 in autophagy and immune response, researchers need to be more careful when evaluating the prognostic value of OTUB1 in different cancers." (PMID 33240928, 2020). "Using qRT-PCR analysis, we found that OTUB1 was highly expressed in RCC tumor tissues compared to adjacent non-cancer specimens." (PMID 32257108, 2020). "Recent studies have indicated that OTUB1 is involved in the invasion and migration of malignant tumors." (PMID 33537306, 2020). "Our study showed that high OTUB1 expression was associated with poorer OS (HR = 2.07, 95% CI = 1.30 to 3.30, P = 0.002) in LIHC cohorts including 370 samples in the pan-cancer dataset." (PMID 33240928, 2020). "Of the up-regulated genes, we observed that the expression of OTUB1 in PCa was higher than para-carcinoma tissue." (PMID 33537306, 2020). "Ovarian tumor domain-containing ubiquitin aldehyde binding protein 1 (OTUB1) is overexpressed in many cancers and plays an important role in tumor progression and metastasis." (PMID 31737118, 2019). "Taken together, these results suggest the role of OTUB1 up‐regulation in promoting cancer development in wt KRAS lung tumors." (PMID 26881969, 2016). "Current research on OTUB1 mainly focuses on the field of cancer." (PMID 40387552, 2025). "Meanwhile, the cancer-inhibiting role of OTUB1 knockdown could be reversed by overexpression of circSEC24B." (PMID 39333496, 2024). "Despite its involvement in various cellular processes like DNA break repair pathway, apoptosis, inflammation, tumor metastasis, and various cancers, the precise molecular function of OTUB1 remains largely unknown." (PMID 38663827, 2024). "Furthermore, overexpression of the cancer stem cell marker CD44 promotes the interaction between OTUB1 and SLC7A11, reducing SLC7A11 degradation and inhibiting ferroptosis." (PMID 39769177, 2024). "In addition, OTUB1 is a deubiquitinating enzyme that influences cancer immunosuppression via regulation of PD-L1 stability and a potential therapeutic target for cancer immunotherapy." (PMID 36369321, 2023).
cancer (continued). "Multiple studies have shown OTUB1 promotes cancer cell proliferation." (PMID 38264570, 2023). "Due to the prominent role of OTUB1 in cancer, OTUB1 is a promising target in cancer therapy." (PMID 38264570, 2023). "In the end, we discuss the possibility of OTUB1 as a therapeutic target in cancer." (PMID 38264570, 2023). "From the perspective of DNA damage repair, the effect of OTUB1 on DNA damage might indicate a bipartite role of OTUB1 in cancer." (PMID 38264570, 2023). "Firstly, OTUB1 contributes to genomic stability and prevents cancer occurrence." (PMID 38264570, 2023). "OTUB1 may play a critical role in cancer treatment because cancer cells rely on a functioning ubiquitin‐proteasome system (UPS), making it an attractive target for developing new therapies with selectivity for tumor cells." (PMID 38069522, 2023). "Notably, multiple pieces of evidence show OTUB1 functions in cancer, DNA damage repair, and immunity." (PMID 38264570, 2023). "Numerous studies have shown OTUB1 plays a prominent role in cancer." (PMID 38264570, 2023). "Studies have revealed relationships between these cancer types and OTUB1." (PMID 38264570, 2023). "In the end, we discuss the perspective that OTUB1 can be a potential therapeutic target for cancer." (PMID 38264570, 2023). "This highlights the role of Otub1 as a potential novel checkpoint target for cancer therapy." (PMID 35747794, 2022). "The inactivation of OTUB1 makes cancer cells sensitive to ferroptosis." (PMID 34996454, 2022). "Collectively, these data suggest that OTUB1 facilitates hypoxia adaptation, which might benefit cancer progression." (PMID 35732631, 2022). "OTUB1 is an essential protein in mammals, has oncogenic properties in several solid tumors, and regulates transcriptional and signaling pathways involved in cancer progression and proliferation." (PMID 35159073, 2022). "We carried further rescue experiments to test if OTUB1 modulated cancer progression through YAP." (PMID 36271031, 2022). "In addition, OTUB1 is overexpressed in cancer cells, making OTUB1 a potential target for ferroptosis-mediated cancer treatment." (PMID 34996454, 2022). "Based on the regulation link, modulation of OTUB1 expression or function could be a promising strategy to treat YAP-driven cancers." (PMID 36271031, 2022). "By interacting with miR-23a-3p/23b-3p/23c, SNHG17 upregulates the expression of UBE2M and OTUB1, which have been demonstrated to play critical roles in the tumorigenesis of human cancers, more importantly promoting cancer cell immunosuppression and resistance to cytotoxic stimulation." (PMID 35864871, 2022). "OTUB1 is involved in regulating the DNA damage response and in the development of several cancers." (PMID 36339263, 2022). "CD44 expression inhibits ferroptosis in cancer cells in an OTUB1-dependent manner." (PMID 36612069, 2022). "In addition, in order to further explore the impact of OTUB1 expression modulation on CRC cancer cell migrative capabilities, wound healing test on DLD1 and HCT116 cell lines were performed." (PMID 35354355, 2022). "In this research, we discovered that OTUB1 upregulation was typical in CRC cancer cells." (PMID 35354355, 2022). "Therefore, in various malignant tumors, OTUB1 acts as a pro-oncogene and promotes tumor progression." (PMID 35494004, 2022). "Clinical tissues and CRC cancer cell lines were utilized to evaluate OTUB1 expression pattern." (PMID 35354355, 2022). "Since OTUB1 is frequently overexpressed in human cancers, high SLC7A11 levels in some cancers might result from post-translational regulation by OTUB1." (PMID 33000412, 2021). "Additionally, another study also reveals that OTUB1 can influence cancer cell immunosuppression through regulating PD‐L1 stability." (PMID 34773364, 2021).